STAT1 (signal transducer and activator of transcription 1)
Diseases named in the same sentence as STAT1 in open-access papers (continued):
Sharing a sentence is not in itself a finding about the gene and the disease.
tumor (continued). "Therefore, we looked for a surrogate marker to discriminate between tumor cell-intrinsic effects of Stat1-Ido1 expression and superimposing stromal effects." (PMID 32444775, 2020). "STAT1 was detected in tumor and stroma cells of Stat1flox/floxApcMin mice." (PMID 32444775, 2020). "In addition to impaired NK cell cytotoxicity and NK cell-dependent tumor surveillance, NK cells from Stat1–/– mice show reduced production of IFNγ in response to stimulation of the NK cell activating receptors (actRs) NK1.1 and NKp46." (PMID 33042133, 2020). "Importantly, STAT1 null tumor cells showed enhanced natural killer cell lysis because of their low protein expression of antigen presentation molecules." (PMID 32641473, 2020). "Taken together, miR-29 directly inhibits B7-H3 expression, but it may also induce its tumor-suppressive behavior by upregulating STAT1 activity." (PMID 31382461, 2019). "Therefore, we propose balancing pro-tumor STAT3 activation with anti-tumor STAT1/STAT2 activation as a novel therapeutic approach." (PMID 31684144, 2019). "This is consistent with prior studies indicating STAT1 may play a role as a tumor suppressor, whose function can inhibit the transcription of MYC." (PMID 31382461, 2019). "Therefore, the therapeutic use of STAT/JAK-modulators should be carefully evaluated for their specific targeting of STAT3 activity while preserving IFNγ-induced STAT1/2 signaling, which appears to be beneficial for anti-tumor immune responses." (PMID 31766350, 2019). "Thus, this study identified GBC patient subgroups and provides new mechanistic insights in the tumor suppressive function of miR-145-5p leading to activation of STAT1 signaling." (PMID 30886199, 2019). "However, there are a variety of studies that demonstrate that down-regulation of STAT1 is related to the enhanced invasion and metastasis of tumor cells." (PMID 31569687, 2019). "Total STAT1 levels appear to be similar in tumour tissue from WT and Casp11−/− colons." (PMID 30538296, 2019). "Thus, our findings are in line with the tumor suppressive function of miR-145-5p and the activation of tumor suppressive STAT1 signaling." (PMID 30886199, 2019). "This may be due to this fact that STAT3 and STAT1 proteins are involved in the progression of several tumor cells." (PMID 31569687, 2019). "The downregulation of Stat1, Stat4 and Stat6 observed in tumour tissue may confirm the reduced response to cytokines of lymphocytes and therefore may indicate a decrease in lymphocyte activation." (PMID 31595196, 2019). "The immunosuppressive phenotype of MDSCs is associated with the expression of p-STAT1.34,35 Treatment with LG268 significantly (p = 0.02) reduced the expression of p-STAT1 by 80% in whole tumor lysates, as observed by western blotting and confirmed by immunohistochemistry." (PMID 31700995, 2019). "However, several oncogenes have been reported to be regulated by STAT1, which are involved in promotion of tumor growth and invasiveness, suppression of immune surveillance, and induction of therapy resistance." (PMID 30456450, 2019). "The microarray data revealed 728 distinctly regulated genes between two populations and the top highly expressed genes (IL2RB, GZMA, GZMB, EMR4, PRF1, CX3CR1, STAT1, and TLR9) in lung-derived Ly6C+ cells from EMT6 tumor-bearing mice are associated with effector T-cell function." (PMID 30926774, 2019). "It has been demonstrated that p-STAT1 remarkably arrests tumor cell growth." (PMID 30456450, 2019). "Having greater STAT1 than STAT3 signaling can promote anti-tumor immune responses." (PMID 31681561, 2019). "In contrast to these varying results in normal tissues, we observed that Senexin B inhibited basal STAT1 S727 phosphorylation in all the tested tumor cell lines of different types (patent application US 2017/0115308A1), and similar results were reported in various transformed cell lines by others." (PMID 31717492, 2019).
tumor (continued). "This was corroborated by co-localization of STAT3 and STAT1 in DFTD tumor cells." (PMID 30645971, 2019). "However, transient overexpression of the constitutive active STAT1-cc mutant restored MHC-I expression on B16F10 tumor cells cultured under OGD to levels, comparable to those of B16F10 cells cultured under normal conditions." (PMID 31196219, 2019). "However, we found that expression of STAT1 is higher in HCC tumor tissues in both our patients and other cohorts from online datasets, consisting of a large number of patients." (PMID 30456450, 2019). "The broad spectrum of biological roles for STAT1 suggests that it could be difficult to target this factor specifically or selectively in tumor cells." (PMID 31730010, 2019). "This means that sustained IFN-γ-STAT1 signaling could lead to chronic inflammation and inflammation-mediated tumor development." (PMID 30987642, 2019). "Thus, the tumor-suppressive or tumor-promoting role of STAT1 largely depends on its phosphorylation status." (PMID 30456450, 2019). "The opposite tumoricidal and protumor effects of IFNγ/STAT1 signaling may be attributed to the difference of the tumor-specific context, the magnitude of the signal, and the microenvironmental cues." (PMID 31113461, 2019). "In addition, cell-autonomous tumor-suppressor functions of STAT1 have also been reported in breast cancer." (PMID 29780381, 2018). "STAT1 expression has been reported to exhibit tumor suppressor." (PMID 29492196, 2018). "Moreover, STAT1 promotes extrinsic, tumor‐suppressive effects by enhancement of tumor immune surveillance through NK‐ and T cells." (PMID 29419930, 2018). "However, there is growing evidence that STAT1 also acts as a tumor promoter since it can enhance resistance to chemotherapeutic agents and radiation in carcinoma." (PMID 29780381, 2018). "STAT1 is involved in cell growth regulation and antiviral and immune defense, such as inflammation and innate and adaptive immunity, antiproliferative responses and tumor suppression, and it participates in crosstalk with other signal transduction pathways." (PMID 29849669, 2018). "STAT1 and STAT3 activation is reciprocally regulated and the components appear to play opposite roles in proliferation, apoptotic death, inflammatory and anti-tumor immune responses: STAT1 is considered to be a tumor-suppressor gene, while STAT3 is regarded as an oncogene." (PMID 29894486, 2018). "Consequently, the prognostic value of tumor cell‐intrinsic STAT1 improved significantly after sex stratification of CRC patients." (PMID 29419930, 2018). "We demonstrate a sex‐specific and tumor‐suppressive function of STAT1 in CRC of humans and mice." (PMID 29419930, 2018). "STAT1 has been reported as a tumor suppressor in breast cancer, multiple myeloma and leukemia." (PMID 29855346, 2018). "In addition to T cell receptors, nitration of C-C motif chemokine ligand 2 (CCL2) chemokine and STAT1 in splenocytes from tumor-bearing mice have been reported." (PMID 30405034, 2018). "Although we did not observe any differences in the CIBERSORT 22 immune subsets between responders and non-responders, of the 6 Rody metagenes that we applied (MHC-I, MHC-II, HCK, LCK, IFN, and STAT1), C+K+ tumours expressed higher levels of the MHC-II metagene (p = 0.0696) than other tumours." (PMID 30478407, 2018). "It exerted the anti-tumor effect through the NF-κB, STAT1 and STAT3 signal pathways, which could re-direct the type of TAMs both in vitro and in vivo." (PMID 30513582, 2018). "STAT1 inhibits proliferation and promotes apoptosis of tumor cells." (PMID 29419930, 2018). "Except for few being chromatin regulators (CGBP, MBD2, and DNMT1), all of these TFs were found to have tumor suppressor functionality (BRCA1, E2F1&2&5&7, EGR1-4, FLI1, NRF1, TFDP2, and STAT1), or indirectly mediate the suppression of tumorigenesis and tumor suppressor activity (SP4 and ZBTB33)." (PMID 29740534, 2018).
tumor (continued). "Importantly, PLZF remarkably increased the mRNA transcription of interferon-induced protein with tetratricopeptide repeat 2 (IFIT2) by increasing STAT1 protein level, a known factor involved in tumor progression." (PMID 29358655, 2018). "STAT1 functions in CRC might be concealed by dual effects in tumor cells and stromal immune cells, which are both affected in STAT1 knockout mice." (PMID 29419930, 2018). "The results indicated that reduced STAT1 expression in CNE-2R inhibited tumor growth in nude mice." (PMID 29492196, 2018). "Furthermore, we found PLZF overexpression inhibited tumor growth and metastasis by activating STAT1/IFIT2 pathway in GBC cells and nude mice." (PMID 29358655, 2018). "Reduced ascites accumulation couldpotentially result from the angiostatic effects of CXCL10, a chemokine that isinduced and released in the TME post-IFN pathway activation via both STING/STAT1 orcould also be due to decreased tumour burden." (PMID 30046165, 2018). "The interferon‐inducible transcription factor STAT1 is a tumor suppressor in various malignancies." (PMID 29419930, 2018). "In the same way, STAT1-deficient mice that are impaired in Th1 cell polarization, exhibited reduced IFN-γ expression and compromised cytolytic and NK lytic activity, failing to control tumor growth in contrast with wild-type mice." (PMID 29780381, 2018). "We report the findings of additional morphological abnormalities in the Stat1−/− mouse that reflect systemic endocrine and environment effects, as well as the identification of a FoxA1+ large oval pale (LOP) cell that appears along some Stat1-null ducts as their hosts approach tumor-bearing age." (PMID 28865492, 2017). "STAT3 has been shown to promote tumor progression, whereas STAT1 tends to suppress it." (PMID 28626343, 2017). "We provide the first experimental evidence that an elevated STAT1 response in these tumours may sensitize them to immunotherapeutic approaches that serve to augment STAT1-driven anti-tumour immune responses, including vaccine-based strategies." (PMID 28276425, 2017). "The increased immunosuppressive environment of MT/Shc313F/313F tumours renders them insensitive to immune checkpoint blockade but their elevated STAT1 status may be therapeutically exploited to sensitize them to vaccination-based therapies." (PMID 28276425, 2017). "Accumulating evidence suggested that STAT1 is a tumor suppressor in various cancer models." (PMID 28431406, 2017). "If this turns out to be the case, one may hypothesize that we can downregulate the ERK activation in order to active STAT1, a apoptosis promoter, to kill the tumor cells." (PMID 28431406, 2017). "To understand how STAT1 may serve an immunosuppressive role, we measured PD-L1 expression levels, which dampens anti-tumour immunity by activating the PD1 immune checkpoint on activated T cells." (PMID 28276425, 2017). "STAT1, first member of this family, is supposed to be a tumor suppressor in breast tumorigenesis." (PMID 28422733, 2017). "On the basis of the observation of a high tumor “excluded infiltrate” mononuclear density, we postulated that the Stat1-null tumor cells might mediate the host immune response through release of cytokines and other growth factors." (PMID 28865492, 2017). "Further studies have shown that NRCP binds to STAT1 and RNA polymerase II, leading to an increase in the expression of downstream target genes such as glucose-6-phosphate isomerase, which in turn affects glycolysis in tumor cells." (PMID 28738810, 2017).
tumor (continued). "By studying ESCC cell lines and tumor samples collected from the Chaoshan areas, we previously published that STAT1 is a tumor suppressor of ESCC and this protein is frequently down-regulated in ESCC; importantly, the STAT1low phenotype significantly correlates with a worse clinical outcome." (PMID 28431406, 2017). "However, the predicted activation of STAT3 rather than STAT1 in the upstream analysis using Ingenuity Pathway Analysis (IPA), suggests a possible negative regulation of IFNG/STAT1 signaling, counter-balancing the inflammatory anti-tumor response." (PMID 29100312, 2017). "However, accumulated data have shown that IFN-γ-induced genes, such as STAT1, promote tumor growth, metastasis, and resistance to therapy." (PMID 28388578, 2017). "Combined, these data suggest that the STAT3 activation status of tumours may dictate whether STAT1 promotes or attenuates anti-tumour immunity, and that the ShcA pathway is an important integrator of this process." (PMID 28276425, 2017). "Considering the chronically elevated STAT1 activation status of MT/Shc313F/313F tumours, we reasoned that they could be sensitized to alternative immunotherapeutic strategies that favour re-activation of antigen-specific tumour immunity." (PMID 28276425, 2017). "Activation of both Stat1 and Stat3 signalling pathways in tumour cells by mMDSCs may account for the induction of EMT/CSC phenotype as assessed by strong upregulation of EMT-related genes such as Vimentin, CK14 and Twist." (PMID 28382931, 2017). "Interestingly, inhibition or depletion of SHP2 in tumor cell lines or treatment with IFNγ induced upregulation of phosphorylated STAT1 (pSTAT1) and restored expression of HLA class I and APM components." (PMID 28611673, 2017). "Moreover, inhibition of expression of JAK1 or STAT1 abrogated the ability of IFNγ to upregulate PD-L1 in the tumor cell, and reduced the ability of these cells to hamper NK-mediated immunotherapy." (PMID 27366948, 2016). "The mean survival of patients with low ph-STAT1 tumour cell expression was 140 months (95% CI 129-151 months) and 10-year survival rate was 68%, whereas the mean survival of patients with high expression was 160 months (95% CI 152-169 months) and 10-year survival rate was 84%." (PMID 27769057, 2016). "We next wondered whether a distinct so far unrecognized transcriptional response may be induced in NK cells in the presence of Stat1-Y701F that may explain the rescue of NK cell-dependent cytotoxicity and tumor surveillance." (PMID 27757297, 2016). "The median survival of patients with tumors showing neither IL-6Rα expression nor STAT1 activity was 52 months shorter than in patient groups with tumor related IL-6Rα expression and/or STAT1 activity implying that presence of Stat1 and/or IL6Rα is beneficial for patient survival." (PMID 27191495, 2016). "Two distinct response patterns upon STAT3 knockdown were observed: in two cell lines, STAT3 impairment resulted in enhanced STAT1 expression and reduced tumor growth; the other two cell lines displayed diminished STAT1 activity combined with accelerated xenograft tumor growth." (PMID 27191495, 2016). "IFN-γ, in turn, induces apoptosis of tumor cells through a STAT1-dependent pathway." (PMID 26938566, 2016). "In addition, STAT1 is known to negatively regulate angiogenesis, tumorigenicity, and metastasis of tumor cells and suppresses mouse mammary gland tumorigenesis." (PMID 27198694, 2016). "That STAT1 is upregulated in pre-transformed cells may reflect the established role of this factor in cell autonomous anti-tumor immune response (pathway ii)." (PMID 27198694, 2016). "Furthermore, IL-6, IL-8 and VEGF production, as well as STAT1 phosphorylation, were increased in tumour tissues of A549-IL-17 cell-bearing nude mice in vivo and in A549 and H292 cells following IL-17 stimulation in vitro." (PMID 27819281, 2016).
tumor (continued). "However, in the other three cell lines we detected significant changes in the levels of cleaved Caspase3 upon STAT3 knockdown in the xenografts, which correlate with the tumor growth pattern and the STAT1 expression levels in the tumors." (PMID 27191495, 2016). "In multivariate analysis, high ph-STAT1 tumour cell expression was not independently associated with CSS (P=0.193)." (PMID 27769057, 2016). "Two characteristic STAT1/3 expression patterns with opposite growth behavior could be distinguished: cell lines with a low STAT1/high STAT3 ratio showed faster tumor growth in xenografts." (PMID 27191495, 2016). "Based on these results, we reasoned that the activation of STAT1 pathway in tumor cells treated with mafosfamide could result from cell-autonomous secretion of cytokines, known to trigger this pathway." (PMID 27791205, 2016). "For example, CDK8/19 inhibitors might modulate antitumor immunotherapy by inactivating STAT1 and stimulating tumor surveillance by NK cells." (PMID 27935476, 2016). "In univariate analysis, high ph-STAT3 but not ph-STAT1 tumour cell expression was significantly associated with improved CSS." (PMID 27769057, 2016). "This independent BC series confirmed an association between ADAR and STAT1 expression but not for HER2 status or tumor size." (PMID 26440892, 2015). "However, accumulating evidences have correlated upregulated STAT1 with cellular resistance to DNA-damaging agents and increased tumor progression in multiple types of cancers." (PMID 25669971, 2015). "To validate these results using another methodology, we decided to evaluate if expression levels of STAT1 and LYZ, two genes related to macrophage-signatures and possibly to M1 polarization, might be associated with the tumor microenvironment profile." (PMID 25978381, 2015). "Interestingly, we identified one regulatory feedback loop between STAT1 and miR-155-5p that is consistently activated in all seven cancer types with its function to regulate tumor-related biological processes." (PMID 26156524, 2015). "In contrast, other groups have found that in certain cellular contexts the STAT1 pathway may mediate tumor cell growth." (PMID 26617467, 2015). "In addition, several studies have shown that STAT1 can also act as a potent tumor promoter for leukemia development and that many T-ALL leukemic cells are dependent upon the TYK2-STAT1-BCL2 pathway for continued survival." (PMID 26205403, 2015). "Stat-1 is a central mediator of interferons and exerts anti-tumor effects." (PMID 25886253, 2015). "Notably, the early 129:Stat1-null host response to the tumor cells was characteristically granulocytic while the early host response in 129SvEv WT was mononuclear and dominated by CD3+ T-cells." (PMID 26075897, 2015). "A recent study by Zimmerman at al. showed that phosphorylation status of pSTAT1 determines its function as a tumor suppressor, with unphosphorylated STAT1 acting as a tumor promoter that acts by elevating resistance to Fas-mediated apoptosis to promote immune escape." (PMID 26362401, 2015). "Our data highlight the tissue specificity function of EBP1 isoforms and demonstrate that only the oncogene p48 activates MHC II expression in human solid tumours, via STAT1 phosphorylation, in order to affect tumour progression by triggering specific immune response." (PMID 26081906, 2015). "Finally, all these factors will need to be considered in any study of tumorigenesis in STAT1 deficient mice, where our data indicate that aberrant MG development directed by the 129:Stat1-null microenvironment leads to increased tumor initiation." (PMID 26075897, 2015).